SPINK2 (serine peptidase inhibitor Kazal type 2)
Description:
As a strong inhibitor of acrosin, it is required for normal spermiogenesis. It probably hinders premature activation of proacrosin and other proteases, thus preventing the cascade of events leading to spermiogenesis defects. May be involved in the regulation of serine protease-dependent germ cell apoptosis (By similarity). It also inhibits trypsin.
Synonyms: HUSI-II; SPGF29
Tractability: Antibody: UniProt places it where antibodies can reach, with high confidence; UniProt predicts a signal peptide or a membrane-spanning region; its Gene Ontology location is reachable by antibodies, with medium confidence. PROTAC: ubiquitination databases record sites on it.
Gene: Protein-coding gene on chromosome 4 (56,809,860 to 56,821,742, reverse strand). Ensembl gene ENSG00000128040.
Subcellular location: Secreted; Cytoplasmic vesicle, secretory vesicle, acrosome
Subcellular location (Human Protein Atlas): Acrosome; Equatorial segment; Predicted to be secreted
Gene Ontology:
Molecular function: protein binding; endopeptidase inhibitor activity; serine-type endopeptidase inhibitor activity
Biological process: spermatid development; acrosome assembly
Cellular component: acrosomal vesicle; extracellular region
Genetic constraint (gnomAD): Loss-of-function variants: 5 observed, 4.83 expected, observed/expected ratio (o/e) 1.04, 90% interval 0.53 to 1.83. That is too few expected variants to judge how well the gene tolerates losing a copy. Missense variants: 118 observed, 122.55 expected, observed/expected ratio (o/e) 0.96, 90% interval 0.83 to 1.12. Synonymous variants: 62 observed, 50.93 expected, observed/expected ratio (o/e) 1.22, 90% interval 0.99 to 1.5.
Homologues: Orthologues: macaque SPINK2 (47% identical), mouse Spink2 (34% identical), rat Spink2 (34% identical), chimpanzee SPINK2 (26% identical). Paralogues in human: SPINK7 (20% identical), SPINK8 (20% identical), SPINK13 (19% identical), SPINK14 (19% identical), SPINK9 (18% identical).
Diseases named in the same sentence as SPINK2 in open-access papers:
SPINK2 is named in the same sentence as 28 diseases in open-access papers, as found by Europe PMC text mining. Sharing a sentence is not in itself a finding about the gene and the disease. The quoted sentences say what the papers report.
Azoospermia (8 papers, 2017 to 2024). Absence of any measurable level of sperm,whereby spermatozoa cannot be observed even after centrifugation of the semen pellet. "Spink2-null males had azoospermia, and a homozygous splice mutation of SPINK2 was found in infertile men." (PMID 35600599, 2022). "Genetic variation of SPINK2 is also reported to be associated with male infertility, where homozygous SPINK2 mutation leads to azoospermia while haploinsufficiency can result in oligozoospermia." (PMID 32529252, 2020). "We observed that in man, the presence of a homozygous SPINK2 mutation leads to azoospermia while a heterozygous mutation can induce oligozoospermia suggesting that SPINK2 haploinsufficiency can result in oligozoospermia." (PMID 28554943, 2017). "In this particular case, we have shown that SPINK2 deficiency can induce azoospermia and demonstrated that unrestricted acrosomal protease activity induces the arrest of spermiogenesis." (PMID 28554943, 2017). "Overall, the Spink2−/− mouse phenotype perfectly mimics the human condition and confirms that SPINK2 deficiency is involved in human azoospermia." (PMID 28554943, 2017). "Studies have also shown that altered (deficiency/decrease) expression of SPINK2 is associated with NOA, azoospermia, and overall, male infertility." (PMID 35207567, 2022). "Comparative gene expression profiling of infertile men diagnosed with azoospermia showed that SPINK2 expression was decreased fourfold compared with fertile men." (PMID 32529252, 2020). "Studying KO mice, we observed that homozygous KO animals also suffered from azoospermia thus confirming the implication of SPINK2 in NOA." (PMID 28554943, 2017). "We sequenced SPINK2 whole coding sequences of 611 patients affected by azoo‐ or oligozoospermia (210 patients with azoospermia, 393 subjects with oligozoospermia and 8 with unspecified cause)." (PMID 28554943, 2017). "In order to further investigate the molecular pathogeny of this SPINK2‐dependent azoospermia, we determined the localization of SPINK2 in human and mouse testis." (PMID 28554943, 2017). "Spink2 KO mice had azoospermia, abnormal sperm morphology, and decreased sperm motility." (PMID 37324270, 2023). "In accord with these findings, we observed that homozygous Spink2 KO male mice had azoospermia." (PMID 28554943, 2017). "We therefore believe that SPINK2, which transits through the same cellular compartments, quenches this premature protease activity and prevents the described cascade of events leading to azoospermia." (PMID 28554943, 2017). "Here, we have clearly demonstrated that the absence of SPINK2 induces azoospermia, a severe infertility phenotype, emphasizing the importance of this family in human pathologies." (PMID 28554943, 2017). "In order to confirm that the absence of SPINK2 leads to azoospermia, homozygous Spink2 KO (−/−) mice were obtained and their reproductive phenotype was studied." (PMID 28554943, 2017).
leukemia (7 papers, 2014 to 2026). A malignant (clonal) hematologic disorder, involving hematopoietic stem cells and characterized by the presence of primitive or atypical myeloid or lymphoid cells in the bone marrow and the blood. "SPINK2 levels are greatly increased in most of the leukemia cell lines that have been examined and this protein exerts a significant effect on tumor progression and response to treatment." (PMID 38388961, 2024). "These splicing perturbations alter the composition of numerous hematopoietic stem and progenitor (KLF2, GATA2, GATA1, SPINK2) or leukemia (LAT2 and NUCB2) regulatory factors." (PMID 36697445, 2023). "The human homolog, SPINK2, is also expressed in some leukemia cells lines." (PMID 24699552, 2014). "Another group built a six-gene leukemia stem cell (LSC) score with the incorporation of DNMT3B, GPR56, CD34, SOCS2, SPINK2, and KIAA0125 expressions for pediatric AML." (PMID 33225420, 2021). "We observed that SPINK2 was significantly increased in AML, even compared with nine samples without leukemia (p=0.022)." (PMID 37359898, 2023).
Infertility (6 papers, 2017 to 2024). "SPINK2 is detected in the seminal vesicle and testis, where its antimicrobic function may be associated with infertility." (PMID 34202399, 2021). "This analysis indicates that SPINK2 defects are extremely rare with an allelic frequency of approximately 1/1,200 in the cohort of infertile men analyzed." (PMID 28554943, 2017). "The rarity of SPINK2 variants and the fact that P2, the father of Br1 and Br2, also harboring a heterozygous mutation, presents in a milder phenotype than P105 could indicate that SPINK2 haploinsufficiency induces a milder phenotype of oligozoospermia with an incomplete penetrance on infertility." (PMID 28554943, 2017). "We can therefore conclude that in mice, SPINK2 haploinsufficiency induces asthenoteratospermia with no alteration of reproductive fitness, whereas in man it leads to oligoteratozoospermia with variable expressivity and infertility with an incomplete penetrance." (PMID 28554943, 2017).
male infertility (4 papers, 2020 to 2025). The inability of the male to effect fertilization of an ovum after a specified period of unprotected intercourse. "SPINK2 deficiency causes male infertility, suggesting an important role in male reproduction." (PMID 36936975, 2023). "Notably, mutations in SPINK2 are associated with oligospermia and male infertility." (PMID 40649876, 2025). "This section will briefly highlight the role of the eight (TNP1, TNP2, PDHA2, LDHC, SPINK2, ODF1, ODF2, and PCDHB3) common DEGs in male infertility as obtained from our findings." (PMID 35207567, 2022).
testicular cancer (4 papers, 2019 to 2024). A primary or metastatic malignant neoplasm that affects the testis. "In the testes, the presence of SPINK2 not only affects sperm quality but also is associated with testicular cancer." (PMID 35223512, 2022). "On downregulation of SPINK2 in testicular cancer tissues, the combined effect of SPINK2 and RARRES1 significantly inhibits testicular cancer cell EMT by downregulating the uPA/uPA receptor signaling pathway." (PMID 38388961, 2024). "On the contrary, a tumor-suppressive role involving the inhibition of the epithelial–mesenchymal transition was also recently described for SPINK2 in testicular cancer." (PMID 37298647, 2023). "The interaction between TIG1 and SPINK2 plays an important role in inhibiting the EMT of testicular cancer cells by downregulating the uPA/uPA receptor (uPAR) signaling pathway." (PMID 35223512, 2022). "Second, our current study observed an interaction between TIG1 and SPINK2, and the association of these two proteins was involved in suppressing the activity of uPA and subsequent effects on EMT and cell migration in testis cancer cells." (PMID 31886233, 2019). "TIG1 and SPINK2 were highly expressed in normal testis tissues, while low expression levels of TIG1 and SPINK2 were found in testicular cancer tissues." (PMID 31886233, 2019). "TIG1 and SPINK2 are downregulated in testicular cancer tissues." (PMID 35223512, 2022). "Therefore, the results suggest that the interaction between TIG1 and SPINK2 plays an important role in the inhibition of testicular cancer cell EMT, and suppression is mediated through downregulation of the uPA/uPAR signaling pathway." (PMID 31886233, 2019). "Although the role of SPINK2 in the testis is still not clear, SPINK2 might regulate cell migration and invasion in testicular cancer cells through the uPA/uPAR system; this is supported firstly by the similar activity of homologous proteins." (PMID 31886233, 2019).
pancreatic cancer (2 papers, 2022 to 2024). "Furthermore, CP is also a risk factor for pancreatic cancer and patients with hereditary pancreatitis associated with SPINK1 and SPINK2 mutations have a 40% lifetime risk of developing pancreatic cancer." (PMID 36500723, 2022).
diffuse large B-cell lymphoma (1 paper, 2021). "SPINK2 upregulation was also found in Diffuse Large B-cell Lymphoma and Primary Cutaneous Follicle Center Cell Lymphoma samples." (PMID 33925480, 2021).
lung carcinoma (1 paper, 2023). "SPINK2 and at least one of the correlated genes, AIF1 (allograft inflammatory factor 1), showed higher expression in female NKs than in male NKs from either PBMCs or the microenvironment of lung cancer." (PMID 36936975, 2023).
myelodysplastic syndrome (1 paper, 2023). A clonal hematopoietic disorder characterized by dysplasia and ineffective hematopoiesis in one or more of the hematopoietic cell lines. "Transcriptome analysis in CD33+BM blast cells purified from a patient with AML transformed from myelodysplastic syndrome showed that the expression of SPINK2 was higher than control CD33+ BM cells." (PMID 37359898, 2023).
testicular embryonal carcinoma (1 paper, 2019). A malignant germ cell neoplasm arising from the testis. "Since TIG1 and SPINK2 are highly expressed in testis tissue, we next detected their mRNA expression in normal testicular cells, testicular embryonal carcinomas, and testicular seminomas." (PMID 31886233, 2019).
cancer (5 papers, 2019 to 2024). A tumor composed of atypical neoplastic, often pleomorphic cells that invade other tissues. "There is a close relationship between the expression of SPINK2 and cancer growth, and high levels of SPINK2 transcript are detected in patients with primary skin follicular center cell lymphoma." (PMID 38388961, 2024). "Though several members of the SPINK gene family, particularly SPINK1, have been associated with aggressive cancer phenotypes, little is known about SPINK2 in cancer and AML." (PMID 37298647, 2023). "The expression of SPINK2 is closely related to the development of cancer, and high levels of SPINK2 transcripts can be detected in patients with primary skin follicular center cell lymphoma." (PMID 35223512, 2022). "Because the SPINK protein family has been shown to inhibit uPA activity, which may contribute to epithelial-to-mesenchymal transition (EMT) and tumor metastasis, we hypothesized that SPINK2 might participate in TIG1-mediated inhibition of cancer cell invasion." (PMID 31886233, 2019). "Decreased gene expression in TIG1 and SPINK2 was observed in cancer tissues, indicating that TIG1 and SPINK2 might participate in cancer development in testicular tissue." (PMID 31886233, 2019). "Moreover, regulation of the uPA system by TIG1 in testis cells may not occur in other cancer cells because SPINK2 is expressed in testis tissue only." (PMID 31886233, 2019).
tumor (3 papers, 2022 to 2024). "Our data reveal a new RARRES1 /SPINK2 axis with a tumor suppressor role in HCC, which decreased cell proliferation and migration and improve HCC cell sensitivity to lenvatinib." (PMID 38388961, 2024). "Our findings highlighted that RARRES1 can inhibit HCC progression and regulate HCC sensitivity to lenvatinib by interacting SPINK2, representing a new tumor suppressor RARRES1/SPINK2 axis in HCC that modulates sensitivity to lenvatinib." (PMID 38388961, 2024). "SPINK2 is significantly elevated in most of the leukemia cell lines studied and plays an important role in tumor progression and response to treatment." (PMID 35223512, 2022). "RT-qPCR and western blot both demonstrated that SPINK2 mRNA and protein levels were markedly lower in HCC tumor samples than those in normal liver tissue." (PMID 38388961, 2024).
SPINK2 also shares sentences with these, for which no sentence is quoted: migraine with aura (3 papers); acute myeloid leukaemia (2); acute lymphoblastic leukemia (1); epilepsy (1); glaucoma (1); hematopoietic neoplasms (1); hepatocellular carcinoma (1); lymphoma (1); men (1); migraine without aura (1); Myelodysplasia (1); myeloproliferative neoplasm (1); oligoasthenoteratozoospermia (1); oligospermia (1); teratozoospermia (1); testicular seminoma (1).